PDGFRA (platelet derived growth factor receptor alpha)
Diseases named in the same sentence as PDGFRA in open-access papers (continued):
Sharing a sentence is not in itself a finding about the gene and the disease.
tumor (continued). "Of note, PDGFRA and KDR are not contiguous in the 4q12 amplicon, and the intermediate gene KIT was also found as singularly amplified in a subpopulation of one tumor." (PMID 37610648, 2023). "The results showed that NEBL, PDGFRA and ZBTB4 were upregulated in OC tissues compared to in normal ovarian tissues, whereas WDR91 were downregulated in tumor tissues." (PMID 34484284, 2021). "PDGFRα was also highly coexpressed by the ASCL1+ and OLIG2+ (not shown) tumor cells, whereas GFAP and to a lesser extent S100β and NEUN, although found in some parts of the tumor, did not overlap significantly with SOX2 or ASCL1." (PMID 32573857, 2020). "On the other hand, in the transition in vitro to in vivo but in absence of KSHV, when tumor cells that lost the KSHV episome form KSHV (-) tumors, we did not found increase in the activation of PDGFRA signaling, with very low level of the PDGF ligands." (PMID 32603362, 2020). "Although, the majority of tumor samples showed no CNA of ALK, PDGFRA, VEGFR2/KDR, FGFR1, and to a lesser extent of MET in both primary and recurrent samples, the concordance of CNA status varied substantially in the subset of cases with alterations." (PMID 30894200, 2019). "We observed increased levels of phosphorylated PDGFRA, total PDGFRA, and phosphorylated AKT in the tumor samples but no significant changes in total AKT levels." (PMID 25748921, 2015). "We selected tumor xenograft models with distinct morphological and molecular characteristics in tumor vascularization and PDGFR expression due to PDGFRA gene amplification respectively independent of their histological type." (PMID 26599335, 2015). "Single-cell suspensions of tumor tissue were gated for non-immune (CD45−), non-epithelial (Ep-CAM−) cells and detected as PDGFRβ+PDGFRα." (PMID 25280532, 2014). "At this time, molecular profiling of the patient primary tumor was performed and it revealed FGFR1 overexpression, SOX2 amplification and no PDGFRA amplification." (PMID 25126591, 2014). "Further categorization of PDGFRα+ CAFs revealed that PDGFRα+/SAA3 (Serum Amyloid A3)+ CAFs could enhance PDAC progression, whereas PDGFRα+ CAFs without SAA expression suppress tumour growth, attributed to Mpp6 overexpression." (PMID 39780187, 2025). "Immunostaining demonstrated that the tumor cells were negative for c-kit, CD34, PDGFRα, and DOG-1." (PMID 34526110, 2021). "Remarkably, PDGFRα and KIT are expressed at much higher levels in the normal kidney than in the tumor cells, showing that targeting of ccRCC by sunitinib is not as cancer-specific as desirable, which may explain observed sunitinib-induced toxicity." (PMID 30881919, 2019). "OS cells (Saos–2 cell line) downregulate the expression of angiogenic factors, such as CD34, PDGFA, PDGFRA, PDGFRB, and VEGF, in human AD-MSCs when co-cultured, implying that MSCs cannot differentiate in vitro under the induction of tumor cells and do not support tumor angiogenesis in vivo." (PMID 34681692, 2021).
cancer (378 papers, 2004 to 2026). A tumor composed of atypical neoplastic, often pleomorphic cells that invade other tissues. "COL1A1+ stromal cells were categorized into four major clusters: cancer-associated fibroblasts (fib), identified by high expression of PDGFRA, were further divided into four subgroups." (PMID 41281745, 2025). "These are clearly relevant and important questions given that dysregulated PDGFRα signaling is associated with poor survival in many cancers." (PMID 40301543, 2025). "Preferential co‐localisation of single cancer cells with the perivascular niche; and association with PDGFRA expression." (PMID 40641450, 2025). "The Asp at position 7 is the Aspβ9 (FLT3 D835, KIT D816, and PDGFRA D842) which is recurrently mutated in many cancer types." (PMID 40831936, 2025). "Immune-related genes, such as COL1A1, ITGB1, THY1, and PDGFRA, have been implicated in various cancers, but their roles in UCEC remain underexplored." (PMID 40817072, 2025). "In contrast, KIT D816V, FLT3 D835Y, and PDGFRA D842V are activation loop mutations commonly found in acute leukemias, gastrointestinal stromal tumors, and other cancer types." (PMID 40831936, 2025). "Collectively, our findings elucidate the distinct biological functions of PDGFRα+ cancer-associated fibroblasts (PDGFRα+ CAFs) within the TME." (PMID 39827226, 2025). "To characterize genomic alterations in our cohort, we performed targeted exome sequencing for 425 cancer-related genes and Sanger sequencing for validation of PDGFRA mutation." (PMID 38764775, 2024). "Dysregulation or mutations in PDGFRα signaling have been implicated in several diseases, including certain cancers, where aberrant activation of this receptor can contribute to uncontrolled cell growth and tumor progression." (PMID 38607023, 2024). "PDGFRA was associated with nine dysfunctional cancer hallmarks (including four proliferation signatures and two development signatures)." (PMID 37491836, 2023). "Aberrant PDGFRA activities have been linked to a variety of diseases, including fibrosis, cancer, and pediatric diseases." (PMID 35212838, 2022). "In conclusion, the CN gain of PDGFRA pathway was identified as a prognostic risk factor for six cancer types: ACC, KIRC, LUAD, SARC, SKCM, and UCEC." (PMID 35212838, 2022). "PDGFRA expression was highest in cancer-associated fibroblasts (CAFs) of PDAC, as validated in public databases and cell lines from our cancer center." (PMID 35378770, 2022). "The results showed that CN gain of PDGFRA pathway in the cancer patients was associated with significantly shorter overall survival." (PMID 35212838, 2022). "On the other hand, cancers that lack KIT or PDGFRA mutations (“wild-type” GISTs) are often unresponsive to such therapy." (PMID 36090331, 2022). "We analyzed the CNVs of each PDGFRA pathway gene in TCGA database for each cancer type and found that the frequency of CN gain or CN loss in PDGFRA pathway varied from one cancer type to another." (PMID 35212838, 2022). "First, we showed that the frequency of CN gain or CN loss in PDGFRA pathway varied among different cancer types." (PMID 35212838, 2022). "Broad-spectrum inhibitors have been successfully utilised in other cancers, such as dual inhibition of PDGFRa and FGFR2 by pazopanib in SMARCB1-deficient rhabdoid tumours." (PMID 34764236, 2021). "Our data faithfully simulate a cancer-associated insulator loss and confirm that it allows the PDGFRA oncogene to engage in multiple long-range interactions with a neighboring TAD, including with a super-enhancer element that likely drives its expression." (PMID 31534142, 2019).
cancer (continued). "Several genes account for a large proportion of variant/drug interactions (e.g., EGFR, KIT, ERBB2, BRCA1, PDGFRA), reflecting interest in therapeutically exploiting a relatively limited number of cancer driver genes." (PMID 30053901, 2018). "The receptor complex activates pathways involved in cell migration and chemotaxis during wound healing; additionally, mutations in PDGFRA play an active role in cancer development." (PMID 29338018, 2018). "The results of preclinical studies and the frequent expression of PDGFRα in many types of cancer and in cancer-associated stroma support a rationale for the clinical development of IMC-3G3." (PMID 24294521, 2013). "Variants in PDGFRA have previously been associated with susceptibility to several cancer types, certain developmental anomalies (see Genetic Association), and several red blood cell quantitative traits." (PMID 23401653, 2013). "Since Hh signaling components and PDGFRα localize to primary cilia in a variety of cell types, we investigated if primary cilia are associated with Hh and PDGFRα signaling in wt and cancer OSE cells." (PMID 23351307, 2012). "Additionally, the correlation between THBS4 expression and cancer-associated fibroblasts (CAFs), specifically the PDGFRA+ inflammatory CAFs, was investigated to understand the stromal regulatory protein’s role in PTMC aggressiveness." (PMID 40303998, 2025). "Additionally, as a receptor tyrosine kinase (RTK), PDGFRA has been reported to be associated with cell proliferation, migration, survival, aggressiveness and poor prognosis of some types of cancers." (PMID 40501228, 2025). "FAP and PDGFRα are known as cancer-associated fibroblasts markers." (PMID 37958844, 2023). "Notably, univariate analysis identified PDGFRA pathway CN gain as a risk factor for poor OS in the following six cancer types: ACC (P < 0.05), KIRC (P < 0.01), LUAD (P < 0.05), SARC (P < 0.05), SKCM (P < 0.05), and UCEC (P < 0.001)." (PMID 35212838, 2022). "Notably, the CN gain of PDGFRA pathway was significantly associated with shorter OS in six cancer types including ACC, KIRC, LUAD, SARC, SKCM, and UCEC, thus serving as a prognostic risk factor for poor OS." (PMID 35212838, 2022). "Interestingly, PTCH1 shows the highest mutation rate in 7% (127/1867; 7%) of cancers, followed by PDGFRA (89/1867; 5%), ABL1 (68/1867; 4%), FOSB (56/1,678, 3%), ALDH1A1 and CCND2 (48/1,678; 2.9%), (55/1867; 2.9%)." (PMID 36704357, 2022). "We hypothesized that this subpopulation of PDGFRα/β+ fibroblasts may be a cancer-associated fibroblast (CAF) population, and we analyzed it further to determine if it expressed a characteristic transcriptome profile." (PMID 34884982, 2021). "Augmented PDGFRα was associated with poor survival of cancer patients." (PMID 33568640, 2021). "Interestingly, in addition to PDGFRA we found four genes previously shown to be driver mutations in different cancers: SETD2, FAT4, TRIP11 and PPP3CA (highlighted genes)." (PMID 32603362, 2020). "Since aberrant PDGFRα signaling is linked to many human tumors, such as gliomas, osteosarcoma, and gastrointestinal stromal tumors, it can be argued that the suppression of the primary cilium can be beneficial for cancer regression." (PMID 30884815, 2019). "Although the role of the PDGFRα signaling/primary cilium in cancer progression remains to be defined, the fact that a loss of the primary cilium can induce either signaling inhibition or hyperactivation indicates that PDGFRα signaling requires the cilium to function correctly." (PMID 30884815, 2019).
cancer (continued). "In our sequencing studies, solely 17.2% of GISTs harbored non-synonymous missense HSD11B1 mutations, and this low prevalence indicated their role as secondary aberrations in the cancer hallmark of metabolic deregulation among the GISTs that mostly manifested mutated-KIT or -PDGFRA." (PMID 30388854, 2018). "Both A2M and PDGFRA with underexpression and somatic mutation can lead to the cancer development." (PMID 25137136, 2014). "Single-cell analysis revealed that LRGS scores were highest in cancer-associated fibroblasts (CAFs), with APOD and SERPINE1 highly expressed in PDGFRA+ CAFs and CA9+ CAFs, respectively." (PMID 42253954, 2026). "Our analysis revealed associations between the expression of COL1A1, ITGB1, THY1, and PDGFRA genes and different cancer stages in UCEC, however, the results were insignificant due to the lesser number of samples." (PMID 40817072, 2025). "Among these, we observed high-frequency variants across 25 cancer-related genes, with complete penetrance notably found for FGFR3 (rs7688609, COSM4533173) and PDGFRA (rs1873778, COSM7410554)." (PMID 41567639, 2025). "In cancer, PDGFRα expression has been identified in GBM and BC stem-like cells, and its activation has been associated with an increase in mesenchymal traits and enhanced tumorigenicity." (PMID 41463341, 2025). "The success of this approach in preselecting compounds with potent PDGFRA inhibitory potential highlights its significance in advancing personalized and targeted therapies for cancer treatment." (PMID 39802474, 2025). "The pathway enrichment analysis showed that PDGFRB and PDGFRA were involved in Reactome pathway R‐HSA‐2219528 (PI3K/AKT Signaling in Cancer), which was overrepresented in DEGs found in the α‐SMA+ stroma of G2 and G3 tumors." (PMID 39245631, 2025). "A 2025 Cancer Cell study reported radiographic responses in PDGFRA‐mutant pHGG patients treated with the inhibitor avapritinib." (PMID 41036308, 2025). "When COL1A1, ITGB1, THY1, and PDGFRA are down-regulated, they contribute to a cascade of molecular events that profoundly impact cancer development and progression." (PMID 40817072, 2025). "We identified three major stromal cell types, including cancer-associated fibroblasts (CAFS; FAP, COL1A1), perivascular-like cells (PVL; PDGFRA, PDGFRB), and endothelial cells (PECAM1, CD34)." (PMID 40858992, 2025). "A previous study showed that PAK1 kinase is stimulated by PDGFRa upon growth factor binding in cancer cells." (PMID 40586933, 2025). "Our analysis of key cancer types revealed differential expression of genes encoding NADH-ubiquinone oxidoreductase and platelet-derived growth factor receptor alpha (PDGFRA)." (PMID 39594421, 2024). "Among the specifically expressed genes of each subgroup, PDLIM1 correlated only with three other cancer stem cell markers, namely PDGFRA, RBP1, and ITM2A." (PMID 39548074, 2024). "PDGFRα remains a significant target for therapeutic interventions, and drugs that inhibit its activity are utilized to treat certain cancers and other conditions driven by abnormal PDGFRα signaling." (PMID 38607023, 2024). "The presence of WNT5A+ inflammatory fibroblasts was confirmed by the overlapping signals from the WNT5A, GREM1, and PDGFRA RNA probes in the desmoplastic stroma of cancer tissues." (PMID 38744958, 2024). "We prepared an in-house library of 804 phytochemicals from these anti-cancer plants and screened them against PDGFRA to predict the best binding affinities." (PMID 39850565, 2024). "We recently uncovered a novel role for autophagy in regulating the signaling and levels of PDGFRA, a receptor tyrosine kinase amplified in several cancers." (PMID 38634484, 2024). "Some targeted drugs, such as imatinib, sunitinib and regorafenib, block cancer cell proliferation and survival by inhibiting aberrant signal activation mediated by KIT or PDGFRA mutations." (PMID 39070147, 2024).
cancer (continued). "Pre-CAFs exhibited a high expression of genes like PDGFRA, POSTN, BMP2, BMP5, CEBPB, and BICC1, associated with the serrated pathway of CRC and cancer progression." (PMID 39456726, 2024). "As shown in paraffin section staining, PDGFRα+ fibroblast populations were more prominently observed in cancer-derived fibroblasts compared with metaplasia-derived fibroblasts in 3-dimensional whole-mount immunostaining." (PMID 37196797, 2023). "We labeled cell types as endothelial cell (Endothelial, gene expression of PLVAP, KDR, PTPRB) and cancer associated fibroblasts cell (CAFs, gene expression of FAP, MMP11, PDGFRB, SFRP2, PDGFRA, ADAMTS2)." (PMID 37065499, 2023). "As shown in the transcriptome analysis, cancer-derived fibroblasts showed an increased proportion of PDGFRα-expressing cells compared with other fibroblasts." (PMID 37196797, 2023). "Our data showed that higher expression of α-SMA or PDGFRα was correlated with worse overall survival, elevated cancer progression and enhanced lymph node metastasis." (PMID 37821657, 2023). "PDGFRα and PDGFRβ proteins are upregulated in stromal cells of human cancers and are expressed in 10–70% of borderline or MPTs." (PMID 36522480, 2023). "Cancers with a larger area under the curve and peak intensity on CEUS were associated with about 4 times the frequency of mutations at rs35597368 in PDGFRA compared with those with a lower area under the curve and peak intensity." (PMID 37120792, 2023). "Sunitinib is a multi-kinase inhibitor, targeting VEGFR1,2,3 and PDGFRα,β, which reduces angiogenesis, resulting in diminished oxygen supply to cancer cells, thereby inhibiting cancer cell growth." (PMID 36275794, 2022). "Since our previous research has revealed the predictive value of PDGFRA in the immune response, investigating the drug sensitivity of PDGFRA will help elucidate the role of PDGFRA in cancer treatment." (PMID 35378770, 2022). "We investigated the copy number variation (CNV) of PDGFRA pathway across all common cancer types as well as its clinical relevance." (PMID 35212838, 2022). "The RT-qPCR results revealed that almost all the IRPM-constructing genes were differentially expressed between BLCA and normal tissues adjacent to cancer, except PDGFRA." (PMID 36421685, 2022). "A third inhibitor, ripretinib (DCC-2618), was designed to inhibit the full spectrum of mutant KIT and PDGFRA kinases in cancers." (PMID 35050442, 2022). "Nevertheless, PDGFRA overexpression was observed in many cancers, which correlated with malignant progression." (PMID 35406617, 2022). "Most cancers presented PDGFRA, PDGFRB, PDPN, ACTA2, and FAP hypermethylation compared to normal samples." (PMID 36032075, 2022). "Here, we observed an increase in LOH (immune escape), CNV burden enrichment, TMB and TNB values in most of the cancer types with the CN gain of PDGFRA pathway, except in ACC and UCEC, suggesting a new research direction for ACC and UCEC." (PMID 35212838, 2022). "The results showed that the DMSO group overexpressed platelet-derived growth factor receptor α (PDGFRα) and Axl tyrosine kinases, both involved in cancer cell proliferation, invasion angiogenesis, and migration." (PMID 36614038, 2022). "Clusters 0, 1, 2, 3, 4, 5, and 6 show expression of classical cancer-associated fibroblast (CAF) markers (FAP, PDGFRA, LOX, and metalloproteinases)." (PMID 34921143, 2021). "PDGFRA is a famous growth factor receptor and has been widely reported to transfer signaling in various cancers." (PMID 34257701, 2021). "In this study, we found that PDGFRα was significantly upregulated in Pten−/− MEFs and the hepatic tissues of Pten conditional knockout mice, as well as human cancer cells and tissues." (PMID 33568640, 2021). "PDGFRA plays a major role in these pathways and is expressed in mesenchymal cells and epithelial cancer cells undergoing EMT." (PMID 34702313, 2021).